PADI4 (peptidyl arginine deiminase 4)
Diseases named in the same sentence as PADI4 in open-access papers (continued):
Sharing a sentence is not in itself a finding about the gene and the disease.
gallstones (2 papers, 2022 to 2024). Solid crystalline precipitates in the biliary tract, usually formed in the gallbladder, resulting in the condition of cholelithiasis. "PADI4 inhibitor or metoprolol, a selective β1-adrenergic receptor antagonist known to dampen neutrophil activity, also reduced the growth of gallstones." (PMID 38539330, 2024).
glioma (2 papers, 2024). A benign or malignant brain and spinal cord tumor that arises from glial cells (astrocytes, oligodendrocytes, ependymal cells). "PADI4 and CRYAB proteins, identified among the most abundant proteins exclusive of ND GBM pre-surgery saliva and classified as proteins elevated in glioma, could have a potential role as disease biomarkers." (PMID 39684695, 2024).
HCMV infection (2 papers, 2021 to 2024). "Even though PADI2 and PADI4 are also marginally increased at the mRNA levels, their overexpression does not match the scale observed during HCMV infection of HFFs, where PADI3 expression remains basically unchanged." (PMID 39201398, 2024).
myeloid leukemia (2 papers, 2016 to 2020). A clonal proliferation of myeloid cells and their precursors in the bone marrow, peripheral blood, and spleen. "PADI4 is upregulated during granulocyte and monocyte differentiation in human myeloid leukemia HL-60 cells." (PMID 33363159, 2020).
type 2 diabetes (2 papers, 2021 to 2025). "To determine the role of NETosis in this process, we performed pharmacological inhibition of NETosis with the peptidyl arginine deiminase 4 inhibitor (PAD4i) GSK484 in db/db mice with 6 months of type 2 diabetes." (PMID 39875729, 2025). "Pharmacological inhibition of NETosis was achieved by i.p. injection of the peptidyl arginine deiminase 4 inhibitor (PAD4i) GSK484 daily for 4 weeks between 6 and 7 months of type 2 diabetes." (PMID 39875729, 2025).
active tuberculosis (1 paper, 2024). "The heterozygous rs11203366 genotype of PADI4 is a protective factor for active tuberculosis in Koreans." (PMID 38524554, 2024).
acute appendicitis (1 paper, 2009). "Smeared expression of PADI4 was also detected in some non-tumor inflamed tissues such as rodents, acute gastritis and acute appendicitis." (PMID 19183436, 2009).
adenoma (1 paper, 2009). A neoplasm arising from the epithelium. "High PADI4 content was observed in breast fibroadenoma and thyroid adenoma samples, consistent with immunohistochemical results of adenomas." (PMID 19183436, 2009). "As many adenomas contain more CD34+ cells, we accordingly observed extensive expression of the PADI4 enzyme in these tissues." (PMID 19183436, 2009).
age-related macular degeneration (1 paper, 2023). Age-related loss of vision in the central portion of the retina (macula), secondary to retinal degeneration. "In the retina, PADI2 and PADI4 are associated with age-related macular degeneration (AMD) in the human retina through their citrullination of proteins." (PMID 37020554, 2023).
ankylosis (1 paper, 2012). Fixation and immobility of a joint. "The hind paws of the CA1-Tg mice showed significant edema, redness and ankylosis with pronounced loss of function on the 92nd day after the first injection of collagen, whereas the hind paws of all immunized PADI4-Tg mice and wild-type mice appeared normal." (PMID 23256642, 2012).
autoimmune thyroid disease (1 paper, 2020). Inflammatory disease of the thyroid gland due to autoimmune responses leading to lymphocytic infiltration of the gland. "We found that patients with allele C rs1748033 PADI4 and its CC genotype predisposes to the occurrence of autoimmune thyroid diseases." (PMID 33193078, 2020). "Allele C rs 1748033 PADI4 and its CC genotype were more frequent in patients with autoimmune thyroid diseases, but it was not statistically significant." (PMID 33193078, 2020).
blepharitis (1 paper, 2023). Inflammation of the eyelids near the eyelashes. "When chronic eyelid inflammation (blepharitis) occurs in the eye, PADI4-mediated aggregated NETs block the meibomian gland (MG), leading to meibomian gland dysfunction (MGD)." (PMID 37020554, 2023).
breast fibroadenoma (1 paper, 2009). "Here, relatively high PADI4 expression was observed in breast fibroadenomas and thyroid adenomas by immunohistochemistry." (PMID 19183436, 2009). "In breast fibroadenoma, thyroid adenoma, and pleomorphic adenoma samples, PADI4 was observed in the endothelial cells of capillaries and gland structures (IRS: 1–6), both of which mainly consist of benign tissues." (PMID 19183436, 2009).
cervicitis (1 paper, 2009). An acute or chronic inflammatory process that affects the cervix. "Meanwhile, plasma PADI4 levels in patients with chronic gastritis, chronic nephritis and cervicitis did not considerably change, or even declined, compared to samples from healthy control patients." (PMID 19183436, 2009).
diabetic retinopathy (1 paper, 2018). "This region spans genes with plausible roles in the development of diabetic retinopathy, (e.g. PADI1, PADI2, PADI3, and PADI4, as well as genes known to be involved in kidney function (CLCNKA and CLCNKB)." (PMID 29444168, 2018).
diverticulosis (1 paper, 2020). "This suggests that the presence of elevated PADI4 levels in CM can be provoked by a wide range of gastrointestinal disorders, possibly including IBS, diverticulosis and small polyps." (PMID 32398859, 2020).
emphysema (1 paper, 2025). "Therefore, in an elastase (ELS)-induced emphysema mouse model, we examined the role of PAD4 using Padi4 gene knockout (KO) mice." (PMID 40565035, 2025).
esophageal tumors (1 paper, 2019). "DC-CIK cells induced with lysate from PADI4-overexpressing ECA-109 cells were injected into nude mice bearing esophageal tumors." (PMID 30944835, 2019).
gastric tumor (1 paper, 2016). "The tumorigenic pathway of PADI4 was analyzed in the gastric tumor-derived MNK-45 cell line using a series of tumorigenesis-related PCR arrays." (PMID 27556695, 2016). "In our previous study, we detected considerably increased transcription and translation of PADI4 in gastric tumor tissues compared with corresponding healthy tissues and stomach leiomyosarcoma tissues using real-time PCR, western blotting and immunohistochemistry." (PMID 27556695, 2016). "The result encourages us to focus on investigating the tumorigenic role of PADI4 in gastric tumors." (PMID 27556695, 2016). "The current study found that stimulation of PADI4 increased CXCR2, KRT14 and TNF-α expression levels, suggesting that increased expression of PADI4 in gastric tumor tissues, as we previously observed, contributes to tumorigenesis by increasing the expression levels of CXCR2, KRT14 and TNF-α." (PMID 27556695, 2016).
Graves disease (1 paper, 2020). Graves' disease is an autoimmune disorder that leads to overactivity of the thyroid gland (hyperthyroidism).It is caused by an abnormal immune system response that causes the thyroid gland to produce too much thyroid hormones. "Genotype and allele frequencies for PADI4 gene polymorphism (rs1748033) in groups with Graves’ disease (GD) and with Hashimoto’s thyroiditis (HT) compared to control group." (PMID 33193078, 2020). "The aim of the study was to analyze the polymorphisms of the IL-2RA (rs7093069), FAIM2 (rs7138803) and PADI4 (rs1748033) genes and their correlation to thyroid hormones and anti-thyroid antibodies in pediatric patients with Graves’ disease and Hashimoto’s thyroiditis compared to the control group." (PMID 33193078, 2020).
IgA nephropathy (1 paper, 2020). "With regard to immune-related nephritis, the fact that PADI4 has been identified as a GWAS risk gene for IgA nephropathy supports the possibility that PADI4 plays a critical role in immune complex-mediated nephritis." (PMID 32655553, 2020).
liver cirrhosis (1 paper, 2009). "In addition, more than 60% of the liver cirrhosis samples showed PADI4 expression (IRS: 3–8)." (PMID 19183436, 2009).
mucinous cystadenocarcinoma (1 paper, 2022). An invasive adenocarcinoma characterized by cystic changes and the presence of malignant glandular cells which contain intracytoplasmic mucin. "The results showed that PADI4 was positive in GC tissues, such as nasointestinal tube and mucinous cystadenocarcinoma of GC patients but was limited in normal gastric tissues." (PMID 35045833, 2022).
myeloid malignancies (1 paper, 2025). "Emerging evidence highlights peptidyl arginine deiminase 4 (PAD4) as a potential therapeutic target in myeloid malignancies." (PMID 41304891, 2025).
neuroblastoma (1 paper, 2018). Neuroblastoma (NB) is the most common solid, extracranial childhood tumor. "Moreover, BPA was shown to increase protein levels of PADI4 via a reactive oxygen species mechanism in neuroblastoma cells." (PMID 30483308, 2018).
Pulmonary hemorrhage (1 paper, 2024). Pulmonary hemorrhage is a bleeding within the lungs. "We observed striking hyperinflammation and lethal pulmonary hemorrhage that was dependent on Syk kinase signaling but independent of canonical peptidyl arginine deiminase 4–dependent (PAD4-dependent) NETosis." (PMID 39352872, 2024).
Splenomegaly (1 paper, 2020). Abnormal increased size of the spleen. "IMQ-treated Padi4 KO (Padi4 KO-IMQ) mice showed a significant reduction in splenomegaly compared with IMQ-treated WT (WT-IMQ) mice." (PMID 32655553, 2020).
subarachnoid hemorrhage (1 paper, 2023). A serious neurological disorder characterized by intracranial hemorrhage into the subarachnoid space. "A recent publication in a subarachnoid hemorrhage brain injury model showed that NLRP-3 inflammasome assembly in neutrophil cells is regulated by peptidyl-arginine deiminase 4 (PAD4) and caspase-1 cleavage and promotes NETosis formation under sterile conditions." (PMID 36835009, 2023).
triple-negative breast carcinoma (1 paper, 2023). An invasive breast carcinoma which is negative for expression of estrogen receptor (ER), progesterone receptor (PR), and human epidermal growth factor receptor 2 (HER2). "Notably, Padi4-high groups showed a decreased DMFS specifically for lung but not for brain, bone or liver metastasis in patients with triple negative breast cancer (TNBC)." (PMID 36973439, 2023).
tumor (129 papers, 2009 to 2026). "Through a comprehensive analysis of PADIs and the stemness across 33 tumour types within the TCGA database, it has been determined that PADI4 exhibits a significant association with the stemness characteristics of OSCC." (PMID 40078091, 2025). "Some studies reported high PADI4 expression in other cancers and showed that PADI4 overexpression is associated with pro-tumorigenic properties such as increased tumor cell proliferation, migration, clone forming ability, and metastasis, and reduced apoptosis." (PMID 38259614, 2023). "BM transplanted from PADI4-deficient mice into genetically engineered oncogene-driven tumor-forming mice limits invasive tumor formation." (PMID 37296983, 2023). "This study used an Illumina SNP microarray and a TaqMan assay to determine the possible association of the PADI4 gene with various tumor risks." (PMID 27556695, 2016). "In the present study, we used an Illumina custom-designed SNP microarray to genotype 59 tag SNPs in the PADI4 locus to determine the association of these SNPs to various tumor types." (PMID 27556695, 2016). "By analyzing levels of PADI4 and cAT, as well as the levels of known tumor markers, we aimed to explore the pathogenic role of PADI4 during carcinogenesis." (PMID 19183436, 2009). "Plasma levels of cAT and PADI4 in patients with these malignancies were significantly associated with levels of known tumor markers." (PMID 19183436, 2009). "Compared with PADI4 expression in the malignant tumors, cAT expression appeared to be more specific to malignant tumors and significantly associated with known tumor markers." (PMID 19183436, 2009). "We aimed to determine the tumor types to which the PADI4 gene has valid susceptibility." (PMID 27556695, 2016). "Because there are more CD34+ cells expressing PADI4 in tumour tissues than in normal tissues, it is postulated that the development of PADI4-expressing tumour cells may be associated with the abnormal proliferation of CD34+ stem cells or their progeny." (PMID 20222985, 2010). "Additionally, PADI4 and cAT levels were significantly associated with higher levels of known tumor markers." (PMID 19183436, 2009). "qPCR analysis revealed that PADI4 expression was significantly elevated in tumor tissues compared to adjacent normal tissues." (PMID 41208994, 2025). "Our results demonstrated that PADI4 knockdown inhibited the expression of tumour stemness markers (including CD133 and Nanog) and spheroid growth." (PMID 40078091, 2025). "These insights enhance the comprehension of how PADI4 affects tumour stemness through PRMT2 citrullination." (PMID 40078091, 2025). "We recently discovered that apoptosis induces peptidylarginine deiminase 4 (Padi4) dependent citrullination of histones and results in nuclear expulsion in tumor cells, which leads to the production of nuclear expulsion products (TuNEPs)." (PMID 40751052, 2025). "Analysis of the correlation between clinicopathologic parameters and PADI4 levels in OSCC tissues revealed elevated PADI4 protein levels in Stages III and IV cancers compared to Stages I and II, indicating a positive association with tumour stage." (PMID 40078091, 2025). "When the subcutaneous tumour is removed, IHC staining suggested that shPADI4 group showed silencing of PADI4 population." (PMID 40078091, 2025). "For example, neutrophils and tumor cells undergo nuclear expulsion via Padi4-mediated citrullination of histones, leading to processes such as neutrophil extracellular traps (NETs) during infection and tumor nuclear expulsion during metastasis or therapy." (PMID 40751052, 2025). "Significant decrease in tumour cell proliferation after PADI4 knockdown was demonstrated via colony formation assay." (PMID 40078091, 2025). "The tumour metastasis assay revealed that PADI4 knockdown significantly decreased the average number of lung metastasis nodules, as shown by HE staining." (PMID 40078091, 2025).
tumor (continued). "The blockade of neutrophils or Padi4-dependent NETosis, in combination with PD-1 inhibition, led to a significant reduction in tumor growth." (PMID 38337844, 2024). "PADI4 as a target for tumor therapy has been preliminarily studied, proving that PADI4 is a feasible target for tumor therapy." (PMID 37804426, 2023). "Nonetheless, we found 46 genes that carried either genomic or transcriptional alterations in all three resistant tumor groups, including 8 genes (Parp3, Gstm1, Il18, Padi4, Dnmt3b, Psrc1, Rif1, and Ankrd26) involved in DDR." (PMID 37209095, 2023). "PADI4 can induce arteriosclerosis by mediating the formation of NETs or promote tumor growth and metastasis by altering the tumor microenvironment." (PMID 37020554, 2023). "Collectively, these results suggest that inflammatory mediators in the lungs enhance Padi4 expression thus potentiating tumor cell nuclear expulsion." (PMID 36973439, 2023). "Although the role of PADI4 in tumors is well understood, the subcellular localization of PADI4 in tumor cells is unclear." (PMID 37804426, 2023). "PADI4 recombinant protein is a macromolecular substance that is difficult to enter cells to play a role but has an effect on immune cells and tumor cells." (PMID 37804426, 2023). "The increased expression of PADI4 reduced, while knockout accelerated tumor cell growth, which is correlated with immune responses, suggesting that PADI4 contributes to tumor suppression by enhancing immune function." (PMID 38132337, 2023). "Second, a myeloid-specific Padi4 knockout mouse model (Padi4myeKO) was established to compare Padi4’s effect on metastasis between tumor cells and the myeloid compartment, as previous studies imply neutrophil-produced and Padi4-dependent NETs in metastasis." (PMID 36973439, 2023). "Other studies observed low PADI4 expression in cancer and found that PADI4 can suppress tumor cell growth." (PMID 38259614, 2023). "Taken together, these data suggest that dying tumor cells undergo Padi4-dependent nuclear expulsion, resulting in NEPs that consist of a decondensed histone–DNA complex marked with citrullination." (PMID 36973439, 2023). "Our data showed that neutrophils sorted from lungs of tumor-bearing mice in the stress group significantly up-regulated the expression of PADI4 at both transcriptional and protein levels." (PMID 37773152, 2023). "Anti-PADI4 antibodies can affect the biological functions of cell membrane PADI4, including proliferation, migration, apoptosis, and glycolysis, thereby inhibiting tumor progression." (PMID 37804426, 2023). "Analysis of tissues revealed that PADI4 protein expression levels in GC tissue tumour samples were increased compared with those in the corresponding adjacent tissues (p = 0.03)." (PMID 35045833, 2022). "PADI4 KO in 4T1 cells effectively inhibited tumor growth in an allograft model and reduced lung metastasis." (PMID 36365233, 2022). "Purification of the PADI4 protein can increase its ability to stimulate DC maturation and tumor growth suppression." (PMID 30944835, 2019). "DC-CIK cells stimulated with lysate from PADI4-overexpressing cells or the PADI4 recombinant protein were injected into the tumor-bearing mice." (PMID 30944835, 2019). "In the present work, we investigated the potential value of PADI4 as a tumor marker in DC-CIK cell immunotherapy." (PMID 30944835, 2019). "This study applied PADI4 as a tumor marker to stimulate DC- (dendritic cell-) CIK (cytokine-induced killer), an immunotherapy approach." (PMID 30944835, 2019).